ENSG00000283128 (novel protein)
Gene: Protein-coding gene on chromosome 7 (155,474,256 to 155,644,406, reverse strand). Ensembl gene ENSG00000283128.
Genetic constraint (gnomAD): Loss-of-function variants: 8 observed, 6.65 expected, observed/expected ratio (o/e) 1.2, 90% interval 0.69 to 1.86. That is too few expected variants to judge how well the gene tolerates losing a copy. Missense variants: 74 observed, 78.94 expected, observed/expected ratio (o/e) 0.94, 90% interval 0.78 to 1.14. Synonymous variants: 23 observed, 29.42 expected, observed/expected ratio (o/e) 0.78, 90% interval 0.56 to 1.11.
Homologues: Orthologues: chimpanzee CNPY1 (98% identical), dog CNPY1 (86% identical), rat Cnpy1 (77% identical), mouse Cnpy1 (75% identical), macaque CNPY1 (72% identical), chimpanzee CNPY1 (62% identical), tropical clawed frog cnpy1 (50% identical), zebrafish cnpy1 (50% identical), Drosophila melanogaster sel (27% identical), Caenorhabditis elegans F01F1.15 (25% identical), Caenorhabditis elegans F01F1.11 (21% identical), Caenorhabditis elegans Y47H9C.8 (18% identical). Paralogues in human: CNPY1 (100% identical), CNPY2 (43% identical).